ANLN (anillin, actin binding protein)
Diseases named in the same sentence as ANLN in open-access papers (continued):
Sharing a sentence is not in itself a finding about the gene and the disease.
cancer (continued). "Specifically, ANLN expression was negatively correlated with the stroma score, immune score, and ESTIMATE scores in six cancers, including CESC, LUSC, SARC, SKCM, STAD, and UCEC." (PMID 36199577, 2022). "To investigate the relationship between ANLN expression and the clinicopathological features of pan-cancer, we evaluated ANLN expression in patients with pathological stages I, II, III, and IV cancers." (PMID 35991576, 2022). "ANLN, which plays a role in inhibiting cancer, and SRPX, which plays a role in promoting cancer, can be used as effective biomarkers to predict the prognosis and the efficacy of immunotherapy." (PMID 35548187, 2022). "The results indicated that the mRNA levels of ANLN, ARNTL2, CDKN3, and FAM53B in the cancer cell lines (SW 1990, BxPC-3, CFPAC-1, and PANC-1) were significantly higher than those in the normal cell line (HPDE), indicating their prognostic value." (PMID 35864471, 2022). "However, the collective migration of cancer cells, a process where two or more cells whose cell–cell junctions are intact move together into nearby tissues and vasculature, could be one explanation for ANLN-mediated cell–cell adhesion." (PMID 34591244, 2021). "However, the association between ANLN and these partners in cancer development has not been fully uncovered to date, and its role in the nucleus remains unknown." (PMID 32560530, 2020). "The present study contributed to an enhanced understanding of ANLN expression for HCC cell growth and provided novel insights into its regulatory mechanism in human cancer." (PMID 30103211, 2018). "Transfection of a miR-497 mimic or small interfering RNAs (siRNAs) against ANLN and HSPA4L inhibited cancer phenotypes in NPC cells." (PMID 26486082, 2015). "Based on a literature survey, we focused our attention on ANLN (anillin, actin-binding protein) and HSPA4L (heat shock 70 kDa protein 4–like) because these two genes are up-regulated in many cancers." (PMID 26486082, 2015). "Together, ANLN and HMGA2 form a novel cancer-promoting axis, which could provide new therapeutic targets." (PMID 41573677, 2025). "While ANLN could be exploited for HCC chemoprevention, it is possible that other gene targets with strong rationales as anti-cancer agents have more potent or less toxic effects." (PMID 40704506, 2025). "The potential prognostic survival benefits of ANLN and ECT2 reported in our study are supported by Zhang and colleagues’ evaluation of the carcinogenic roles of ANLN in various types of cancers via a pan-cancer analysis utilizing the TCGA-GTEx database." (PMID 38785827, 2024). "High expression of ANLN and ASPM was associated with poor overall survival.The qRT‐PCR results revealed that ANLN and ASPM genes were upregulated in BLCA, and there was a correlation between the expression of ANLN and ASPM in cancer tissues and paracancerous tissue." (PMID 37051591, 2023). "In addition, we further investigated the relationship of ANLN and various clinicopathological parameters of NSCLC and its gene expression profile in different cancer types." (PMID 37007961, 2023). "In addition, the expression levels of ANLN, ARNTL2, CDKN3, and FAM53B were upregulated in cancer tissues from our cancer center." (PMID 35864471, 2022). "ANLN and UBE2T are widely expressed in various cancer tissues." (PMID 35578283, 2022). "There were also some IHC data of ANLN showing high and medium staining in cancer samples, although mRNA expression levels were not significantly different between cancerous and non-cancerous samples in our seven patients." (PMID 35444699, 2022). "However, recent studies have provided novel evidence that ANLN may serve as a nuclear regulator for transcriptional reprogramming and control intercellular adhesion and cellular motility to alter the phenotypic plasticity of cancer cells, thus exerting its tumor-promoting functions." (PMID 35340220, 2022).
cancer (continued). "Although previous studies have shown that ANLN is related to carcinogenesis, no pan-cancer analyses of ANLN have been reported." (PMID 35568883, 2022). "Although ANLN has been suggested to be a promising new target in cancer treatment, no pan-cancer analysis of this actin-binging protein has been reported." (PMID 35340220, 2022). "These cooperative regulations of two ANLN splicing isoforms highlighted the biological functions and regulatory mechanism of ANLN in HNSCC tumorigenesis, which might provide new perspectives for cancer therapy." (PMID 34344861, 2021). "Taken together, ANLN and HIST1H1C play potential oncogenic roles in most types of human cancers." (PMID 32966237, 2020). "Although many studies have shown the impact of ANLN on several hallmarks of cancer, some hallmarks have not yet been studied much." (PMID 32560530, 2020). "Among them, we selected the actin-binding protein gene ANLN because our past studies showed that several actin-binding protein genes (CORO1C, FSCN1,LASP1 and MSN) were overexpressed in cancer tissues and were deeply involved in promoting human cancer cell migration and invasion." (PMID 28881803, 2017). "We used an approach for dynamic proteomics to measure the protein levels of PRC1 (protein regulator of cytokinesis 1, NM_003981), ANLN (anillin, NM_018685) and YB1 (Y-box binding protein-1, NM_004559) in individual living human cancer cells over several cell cycles." (PMID 19381343, 2009). "In addition to the cancers mentioned in the introduction section, functional experiments confirmed that the proliferation, migration, and invasion potential of BLCA cells was hindered by ANLN knockdown." (PMID 36199577, 2022). "Moreover, ANLN was related to the infiltration of CD8+ cell and PD-L1 expression in BLCA and could thus act as an indicator to predict the reactivity of the cancer to PD-L1 inhibitors." (PMID 36312898, 2022). "Specifically, ANLN, ARNTL2, TOP2A, PLAU, and VCAN expression are important in the invasion of the basement membrane, intravasation, extravasation, and colonization at secondary sites, but only TOP2A and ARNTL2 contribute to the survival of cancer cells while in circulation." (PMID 34591244, 2021). "There is evidence showing that ANLN plays a critical role in driving cell proliferation, and the absence of ANLN could hinder cancer cells from division." (PMID 32560530, 2020). "ANLN could be a component of the PI3K/Akt pathway that plays a significant role in the metabolism of insulin-mediated glucose or in metabolic reprogramming in terms of glucose, glutamine, nucleotides and lipids in cancer." (PMID 32560530, 2020). "Additionally, mRNA and protein levels of ANLN were also upregulated in primary cancer tissues compared with those in adjacent non-tumor tissues of 81 and 9 cases of fresh HCC samples, respectively." (PMID 30103211, 2018). "However, no pan-cancer analyses of ANLN in various types of tumors has been reported, and it is unclear whether ANLN has critical roles in multiple types of cancer through a common molecular mechanism." (PMID 35568883, 2022). "In addition, it appears that ANLN is redistributed to the leading edge of neuroblasts of C. elegans neurons, not cancer cells, thereby suppressing the F-actin cleavage of cofilin, stabilizing the F-actin network, and regulating cell migration and neurite growth." (PMID 32560530, 2020).
tumor (89 papers, 2012 to 2026). "Single-cell analyses showed that ANLN was predominantly expressed in epithelial and proliferating tumor cells and was associated with microenvironment remodeling, enhanced proliferative and migratory programs, and progression toward an invasive phenotype." (PMID 42074579, 2026). "The underlying mechanisms of ANLN overexpression in several tumor types mainly focused on transcriptional and post-translational regulation." (PMID 41513610, 2026). "Elevated ANLN expression is significantly associated with N stage, M stage, tumor grade, clinical stage, and T stage in ccRCC." (PMID 41573677, 2025). "The results showed that the transcription levels of ANLN was highly expressed in most tumor samples and associated with prognosis of LUAD patients." (PMID 40761262, 2025). "Research has demonstrated a gradual increase in ANLN expression levels from normal tissue to benign lesions and tumor tissue, indicating a close association with tumor development." (PMID 38398143, 2024). "More recently, ANLN is found to be increasingly expressed in multiple malignancies and is strongly associated to tumor initiation and progression 15-20 and notably in HCC it is overexpressed and associated with poor prognosis." (PMID 36923927, 2023). "In the present study, we provided evidence of an association between ANLN expression and various tumor types based on a combined multidatabase." (PMID 35340220, 2022). "Nuclear ANLN overexpression is significantly correlated with tumor stage, histological grade, and tumor invasion; additionally, it is an independent risk factor for DSS." (PMID 35991576, 2022). "To further investigate ANLN expression, we evaluated the association between ANLN expression and pathological tumor stage using the “Stage Plot” module in GEPIA2." (PMID 35568883, 2022). "ANLN expression is significantly associated with the immune checkpoint biomarkers and tumor immunity." (PMID 35340220, 2022). "There was evidence showing that poor tumor prognosis was associated with overexpressed ANLN in the nucleus, consistent with the conclusion of this study." (PMID 34743685, 2021). "In one study, a highly-expressed ANLN protein was proven to be implicated in the metastatic risk of tumours." (PMID 32560530, 2020). "Evidence has shown an association between poor tumour prognosis and highly expressed ANLN in the nucleus." (PMID 32560530, 2020). "Results revealed that high ANLN expression had a significant association with a large tumor size (P = 0.008), a high TNM stage (P < 0.001), a high AFP level (P = 0.002), a poor differentiation (P = 0.003) and death events (P = 0.004)." (PMID 30103211, 2018). "ANLN has been associated in diverse forms of neoplastic disease in man with a proposed role in regulating intercellular adhesion in the epithelia." (PMID 28222102, 2017). "Additionally, correlation analysis revealed a significantly positive association between ANLN expression and tumor mutation burden (TMB), microsatellite instability (MSI), immune cells infiltration." (PMID 36030492, 2023). "The association between ANLN expression and tumor stemness was subsequently performed." (PMID 36199577, 2022). "Taken together, our findings suggest that ANLN can be used as an onco-immunological biomarker and could serve as a hallmark for tumor screening, prognosis, individualized treatment design, and follow-up." (PMID 35991576, 2022). "In this study, we utilized multiple databases to explore the function of ANLN in various human tumors by evaluating the its RNA and protein expression patterns and the associations with prognosis of survival, tumor cell immune infiltration, immune neoantigens, and immune checkpoints." (PMID 35340220, 2022). "In addition, human tumor metastatic and progressive potential is closely associated with the expression levels of ANLN." (PMID 36199577, 2022). "Furthermore, we found that ANLN was associated with the immune cell activity in the BLCA tumour microenvironment." (PMID 36312898, 2022).
tumor (continued). "Notably, however, most genes associated with the role of ANLN in tumor progression were related to cellular biology or the microstructure of actin, such as actin binding, actin filament binding, motor activity, ATPase activity, and structural constituents of the cytoskeleton." (PMID 35568883, 2022). "Furthermore, ANLN could be an onco-immunological biomarker and could serve as a hallmark for tumor screening, prognosis, individualized treatment design, and follow-up." (PMID 35991576, 2022). "In addition, we detected the splicing variants of ANLN in diverse tumor cell lines." (PMID 34344861, 2021). "Then we further identified that ANLN-mediated Hippo signaling suppression is dependent on active RhoA-GTP, which is also crucial for ANLN-mediated promoting-tumor in ICC." (PMID 41513610, 2026). "Conversely, ANLN deficiency leads to cytokinesis failure and DNA damage in ICC cells, thus inducing mitotic catastrophe and suppressing the tumor growth." (PMID 41513610, 2026). "The cytoskeleton protein, anillin (ANLN), has been reported to contribute to various tumor growth by participating in cytokinesis via RhoA signaling." (PMID 41513610, 2026). "Examination of subcutaneous xenograft models indicated that ANLN knockdown slowed tumor growth in vivo." (PMID 41513610, 2026). "RT-qPCR validated differential expression of WDR72, ANLN, and SLC16A12 in normal renal versus ccRCC tumor tissues, supporting their potential as diagnostic and therapeutic biomarkers." (PMID 41332473, 2025). "As a downstream effector of the MIR600HG/hsa-miR-342-3p axis, ANLN influences tumor immune responses by regulating the expression of CCL5 and CCL14, thus altering the infiltration levels of helper T cells(Th2) and effector memory T cells(Tem)." (PMID 41573677, 2025). "In vivo data revealed that ANLN knockdown partially reversed the tumor growth-promoting effect of CCNE1 overexpression." (PMID 40346052, 2025). "By the GEPIA platform, we conducted an expression analysis at the RNA level and discovered significant upregulation of SERPINB3, LY6D, DCBLD2, and ANLN within PC tumor tissues." (PMID 41427028, 2025). "Current studies indicate that ANLN promotes tumor progression by regulating the cell cycle, cytoskeletal dynamics, and multiple oncogenic pathways, including RhoA and PI3K/AKT." (PMID 41573677, 2025). "Meanwhile, numerous bioinformatics studies and lstructions have found that ANLN is a potential biomarker related to predicting prognosis, and can affect the neoplasm immune microenvironment." (PMID 41573677, 2025). "ANLN is also highly expressed in human gastric cancer tissues, and its expression significantly correlates with tumor size and pTNM stage." (PMID 41573677, 2025). "To account for this variability, we used multiple tumor assays to support the robustness and context-independence of ANLN as a target for chemoprevention." (PMID 40704506, 2025). "Microarray analysis demonstrated a significant increase in ANLN mRNA expression levels in GBC tissues when compared to adjacent non-tumor tissues." (PMID 38398143, 2024). "Among hypoxia-relevant genes, ANLN is required for tumor growth, and targeting ANLN mitigates tumorigenesis and tumor growth in HCC." (PMID 37481543, 2023). "The immunohistochemical and mRNA results demonstrated that ANLN expression was significantly higher in tumor tissues than paracancerous samples." (PMID 36030492, 2023). "We further explored the clinical implication of ANLN, and its protein expression showed a gradually increasing trend from grade I to III, revealing its association with tumor aggressiveness." (PMID 37007961, 2023). "Second, our study was a retrospective study, so future prospective researches are needed to verify the correlation between ANLN expression and patients' prognosis and tumor immunity." (PMID 36030492, 2023).
tumor (continued). "Considering the strong correlation between ANLN expression and tumor immune landscape, our study next explored the immunotherapeutic predictive ability of ANLN in an anti‐PD‐L1 cohort (IMvigor210)." (PMID 36030492, 2023). "ANLN (Anillin), an actin-binding protein, is dysregulated in expression in various tumors, including PC, and is involved in tumor growth and metastasis." (PMID 37845218, 2023). "ANLN expression was significantly higher in tumor samples than normal tissues in BLCA, CRC (including COAD and READ), LUAD, OV, and TGCT." (PMID 36030492, 2023). "Through interactions with cytoskeletal components, ANLN is involved in regulating tumor cell growth, invasion, and metastasis." (PMID 35991576, 2022). "To gain a thorough knowledge of ANLN’s possible molecular processes in tumor development and progression, we explore the enrichment analysis of ANLN co-expressed genes." (PMID 36199577, 2022). "The results of qRT-PCR uncovered that ANLN expression was higher in tumor tissues than that in adjacent tissues (P < 0.01)." (PMID 36482354, 2022). "We next investigated ANLN-interacting proteins and the genes associated with ANLN expression for a series of pathway enrichment analyses to observe the molecular mechanism of ANLN in the tumor progression." (PMID 35340220, 2022). "For LIHC, T stage (T3/T4, HR = 2.28, p-value < 0.001), tumor status (with tumor, HR = 1.91, p-value = 0.007), ANLN expression (high ANLN, HR = 1.61, p-value = 0.042) were independent prognostic factors." (PMID 36199577, 2022). "ANLN was overexpressed in various tumor tissues compared with corresponding normal tissues, and significant correlations between ANLN expression and patient prognosis, genetic alterations, phosphorylation levels, and immune infiltration were noted." (PMID 35568883, 2022). "In normal conditions, ANLN inhibition results in activation of apoptosis signaling and DNA damage checkpoints, while high ANLN expression promotes tumor growth." (PMID 35954483, 2022). "In the present study, we investigated several types of ANLN protein phosphorylation and compared the phosphorylation levels of ANLN between the main tumor and normal tissues using the CPTAC database." (PMID 35340220, 2022). "We found that ANLN mRNA expression was positively correlated with cell cycle progression; moreover, most tumors showed high ANLN expression, which was significantly correlated with poor prognosis and tumor progression." (PMID 35991576, 2022). "We subsequently compared the different phosphorylation features of ANLN in normal and tumor tissues by utilizing the CPTAC dataset." (PMID 35340220, 2022). "Third, more work is needed to evaluate the effects of ANLN on promoting tumor occurrence and progression." (PMID 35568883, 2022). "Nonetheless, further experimental studies are warranted to reveal the mechanisms through which ANLN gene alterations are involved in tumor development." (PMID 35991576, 2022). "The results consistently indicated that ANLN showed significant and higher expression in tumor tissues." (PMID 36199577, 2022). "First, we obtained the top 100 ANLN co-expressed genes after combing all TCGA tumor expression data." (PMID 36199577, 2022). "Previous research has demonstrated that ANLN mRNA expression is upregulated in cancerous tumors by 2 to 6 fold, which is higher than the fold of Ki-67, a famous tumor proliferative nuclear marker." (PMID 36199577, 2022). "Research has shown that the ANLN protein level is increased in BLCA and is associated with the tumour stage, grade, and prognosis." (PMID 36312898, 2022). "This suggests that T-cell rejection is the main mechanism through which ANLN regulates immune cell tumor escape, tumor promotion, and metastasis." (PMID 35991576, 2022). "Based on the TCGA database, we analyzed the relationship of ANLN with tumor immune cell infiltration." (PMID 35991576, 2022).